MIF (macrophage migration inhibitory factor)
Diseases named in the same sentence as MIF in open-access papers (continued):
Sharing a sentence is not in itself a finding about the gene and the disease.
melanoma (continued). "Given the prevalence of natural genetic variation in human MIF expression and prior studies correlating high genotypic MIF alleles and immune infiltration in patient tumors, we also analyzed a cohort of patients with melanoma for MIF alleles and clinical presentation." (PMID 41122966, 2025). "Indeed, they showed that peripheral macrophages and TAMs from melanoma models of MIF deficient mice had an elevated expression of pro-inflammatory cytokines and a reduced production of genes playing anti-inflammatory and immunosuppressive roles compared to melanoma models of wild-type mice." (PMID 31013837, 2019). "After establishing that MIF expression is important for the maintenance of melanoma cells in vitro, we investigated whether MIF expression levels were also elevated and/or associated with clinical outcomes in melanoma." (PMID 25168062, 2014). "Similarly it is known that tumour-associated macrophages can enhance melanoma growth though secreted factors and equally there are other infiltrating cells such as lymphocytes which are also potential sources of MIF." (PMID 25168062, 2014). "In serum from patients with advanced melanoma, levels of sCD74 are elevated, and a high sCD74/MIF ratio in those patients predicts longer survival." (PMID 41597203, 2026). "Both recombinant and macrophage-derived sCD74 suppressed melanoma growth and triggered apoptosis by inhibiting the MIF/CD74/AKT survival pathway." (PMID 41597203, 2026). "In soft-tissue sarcoma, tumor-secreted MIF shaped macrophages to become more pro-tumorigenic, and in melanoma, MIF tuned myeloid-derived suppressor cells to hinder cytotoxicity of T cells." (PMID 39908652, 2025). "Shvefel and colleagues identified tumor‐secreted macrophage migration inhibitory factor (MIF) as an upregulated cytokine that mediates immune resistance in melanomas with low‐intratumoral heterogeneity." (PMID 40131169, 2025). "Combining anti-MIF with anti-PD-1 therapy enhances immune activation, reduces tumor growth, and improves survival in melanoma, highlighting potential for clinical application." (PMID 41122966, 2025). "In patients with melanoma, the high-MIF expression genotype (-173C/C) occurred at higher frequencies compared with healthy controls." (PMID 41122966, 2025). "Shvefel and colleagues have identified MIF as a prominent upregulated cytokine responsible for mediating immune resistance in melanoma in a detailed multiomics study." (PMID 40131169, 2025). "In melanoma cell lines, MIF knockdown led to reduction in the cell number and viability over five days with a notable decline after three days." (PMID 41159021, 2025). "Conversely, YUMMER1.7 tumor cells showed a marked reduction in Ccl, Cxcl, Thbs, Visfatin, and Laminin signaling after anti–PD-1/anti-MIF treatment, indicating a disruption of key pathways involved in melanoma invasion, metastasis, and immune evasion." (PMID 41122966, 2025). "Increased MIF expression has been correlated clinically with aggressive disease or increased tumor angiogenesis in patients with melanoma, glioblastomas, non–small cell lung cancer, and head and neck cancer." (PMID 41122966, 2025). "In turn, the secretion of soluble CD74 (sCD74) was observed in melanoma cells and macrophages, while sCD74 suppressed melanoma cell growth and induced apoptosis, inhibiting the MIF/CD74/AKT pathway under IFN-γ stimulation." (PMID 40108693, 2025). "Shvefel and colleagues have identified a key role for MIF in tumor progression in melanoma clones with low tumor heterogeneity." (PMID 40131169, 2025). "Activation of CD74 by MIF contributes to melanoma progression, as presented by its influence on immune responses like TNF-α signaling and apoptosis in the TME." (PMID 41159021, 2025). "Macrophage migration inhibitory factor (MIF) is an upstream regulatory cytokine that is associated with advanced disease and poor outcomes in multiple cancer types, including melanoma." (PMID 41122966, 2025).
melanoma (continued). "Western blot analysis confirmed MIF knockdown across six melanoma cell lines, with substantial reductions in Akt phosphorylation in MelCV, Me1007, and MelRMu cells (40–70% decrease), which corresponded with significant cell proliferation inhibition." (PMID 41159021, 2025). "As CD74 is found primarily on immune subsets where it is associated with improved outcomes in melanoma, we evaluated the ratio of CD74 to its ligands MIF and DDT." (PMID 39028303, 2024). "To assess differential gene expression across common melanoma subtypes (acral, mucosal, sun exposed, and uveal), we analyzed MIF and DDT levels using the Kruskal-Wallis test." (PMID 39028303, 2024). "Overexpression of MIF has been observed in different types of tumours, such as genitourinary cancer, melanomas, and head and neck cancers." (PMID 38520216, 2024). "A previous study showed that enhanced CD74/MIF interactions activated the PI3K/AKT pathway in melanoma and resulted in the promotion of tumor survival." (PMID 38256356, 2024). "In melanoma murine models, administration of the MIF small molecule inhibitor 4-IPP reduces tumor burden and metastasis, and the response is further augmented by co-administration of immune-checkpoint blockade antibodies." (PMID 39028303, 2024). "In melanoma, inhibiting MIF improves the response to immune checkpoint blockade by potentiating CD8+ T-cell infiltration and by reorienting MΦ polarization to a proinflammatory M1-like phenotype." (PMID 38548753, 2024). "It is relevant to this point that MIF has been shown to be immunosuppressive in the context of melanoma." (PMID 38730725, 2024). "Some study showed that MIF inhibition as a strategy for overcoming resistance to immune checkpoint blockade therapy in melanoma." (PMID 38685050, 2024). "In vitro, elevated levels of MIF correlate with increased rates of growth and angiogenesis in human melanoma cell lines, and DDT knockdown correlates with reductions in proliferation markers and increases in apoptotic markers." (PMID 39028303, 2024). "Recent evidence suggests MIF as a therapeutic target in immune checkpoint inhibition (ICI) resistant melanomas, however clinical evidence of MIF and particularly of DDT remain limited." (PMID 39028303, 2024). "Clinically, elevated serum levels of MIF have been observed in patients with advanced melanoma and correlate with poor response to anti-CTLA-4 therapy." (PMID 39028303, 2024). "The potential of targeting the MIF in melanoma immunotherapy is indeed a promising avenue for exploration." (PMID 37454231, 2023). "Their study revealed that inhibition of the MIF blockade in combination with ipilimumab (anti-CTLA-4) improved the response to anti-CTLA-4 treatment in resistant melanoma." (PMID 37725261, 2023). "Perturbation of macrophage migration inhibitory factor expression in mouse melanoma suppresses tumor formation by up-regulating Thrombospondin-1 (TSP-1)." (PMID 37744272, 2023). "In another study, a macrophage migration inhibitory factor (MIF) was identified that enhances the immunosuppressive capacity of MDSCs in late-stage melanoma patients." (PMID 37046685, 2023). "Melanoma-derived MIF suppresses NK cells-mediated killing of uveal melanoma cells, thus maintaining an immunosuppressive TME." (PMID 35842634, 2022). "We found that keratinocytes secrete IL18, IL1ra, MIF and Serpin E1, level of which was increased in keratinocytes incubated with melanoma-conditioned media, as compared to control cells." (PMID 36123693, 2022). "On the other hand, serum MIF levels were enriched in melanoma patients in cohort 1 when considered separately by stage, as well as in all melanoma patients compared with NHDs." (PMID 35121729, 2022). "In the current study, the combination of sCD74 and MIF was a significant survival predictor for melanoma patients with advanced stage." (PMID 35121729, 2022).
melanoma (continued). "In melanoma, MIF/CD74 cannot only regulate the expression of PD‐L1 but also affect the anti‐tumour immune response of macrophages and dendritic cells." (PMID 35060345, 2022). "Evaluation of these associations with larger cohorts would help identify the potential cellular sources responsible for circulating sCD74 and MIF in melanoma." (PMID 35121729, 2022). "Our findings demonstrate that the interplay between sCD74 and MIF regulates tumor progression and determines patient outcomes in advanced melanoma." (PMID 35121729, 2022). "Serum concentrations of sCD74 and MIF in two independent cohorts of melanoma patients and in NHDs were measured." (PMID 35121729, 2022). "We validated that serum sCD74 and MIF levels were elevated in patients with stage-IIIB/C melanoma in cohort 2 compared with NHDs." (PMID 35121729, 2022). "A prospective study with larger sample size is necessary to validate the impact of serum sCD74 and MIF levels on melanoma-patient survival." (PMID 35121729, 2022). "In this study, we sought to determine the clinical implications of sCD74 and their biological functions upon interaction with MIF in melanoma." (PMID 35121729, 2022). "MIF has a role in M2 polarization of macrophages, and MIF has been shown to be expressed by melanoma macrophage fusion cells derived from patients." (PMID 32182935, 2020). "This requirement for stromal MIF in promoting tumor burden phenotypes is consistent with other reports showing that loss of stromal MIF reduces MDSC accumulation and/or tumor growth in de novo oral carcinogenesis and human melanoma." (PMID 33324425, 2020). "Both MIF produced by melanoma cells as well as MIF produced by the stroma are also implied in tumor angiogenesis by acting on other signaling pathways, including the hypoxia-induced factor HIF-1α and the vascular endothelial growth factor VEGF." (PMID 31013837, 2019). "MIF is commonly secreted by B16F10 in cultured melanoma cells, as detected in the conditioned medium." (PMID 32010152, 2019). "Another important point regarding the link between MIF activity in melanoma and immunity concerns the production of interferon-γ (IFN-γ) by immune cells." (PMID 31013837, 2019). "For example, the treatment of melanoma bearing mice with anti-MIF antibodies led to a significantly reduced angiogenesis." (PMID 31013837, 2019). "Another study using an interfering MIF RNA introduced into melanoma cell lines showed a significantly delayed tumor development linked to a marked absence of intra-tumoral vascularization." (PMID 31013837, 2019). "Altogether, many in vitro studies have proven that MIF expression is higher in melanoma cells, especially in case of aggressive disease." (PMID 31013837, 2019). "The discovery that Rb9 binds to rCD74 and rMIF, and the fact that melanoma cells in vitro and metastatic tumors secrete MIF, prompted us to functionally compare Rb9 with peptide C36L1." (PMID 32010152, 2019). "Many in vivo studies have shown a link between MIF production by melanoma cells and angiogenesis in melanoma models." (PMID 31013837, 2019). "Their Northern and Western blot analyses showed that the expression of MIF mRNA and the production of MIF protein were much higher in human melanoma cell lines than in normal cultured melanocytes." (PMID 31013837, 2019). "This study also showed the interest of evaluating MLANA and MIF expression in circulating melanoma cells in order to identify early stage patients with more aggressive disease." (PMID 31013837, 2019). "The results revealed that the MIF amount in serum is higher in melanoma patients than in healthy controls." (PMID 31013837, 2019). "Some data also highlight the implication of MIF in angiogenesis, immunity and metastasis in melanoma cell lines, as well as the availability of different therapeutic options targeting MIF for the treatment of metastatic melanoma." (PMID 31013837, 2019). "Here, we review the published experimental and clinical data for MIF and its involvement in melanoma." (PMID 31013837, 2019).
melanoma (continued). "In vitro studies on melanoma cell lines also showed that MIF knock-down resulted in a reduced expression of VEGF, and this was associated with a decreased response to hypoxia." (PMID 31013837, 2019). "By regulating all these factors, MIF is crucial in the development of immunotolerance and immunosuppressive mechanisms in the case of melanoma." (PMID 31013837, 2019). "All these observations tend to indicate that molecules targeting MIF should allow the restauration of immune mechanisms against melanoma cells." (PMID 31013837, 2019). "Once again, they showed that MIF produced by the host matters more than MIF produced by melanoma cells." (PMID 31013837, 2019). "Translational regulation mechanism(s) and impact of MIF localization on the melanoma progression still need to be further studied." (PMID 31013837, 2019). "The authors also showed that MIF inhibition led to a reduction of melanoma TAM and MDSC-mediated immune suppression." (PMID 31013837, 2019). "As melanoma is a cancer characterized by an altered redox status, these observations were crucial to understand the role of MIF in such disease." (PMID 31013837, 2019). "All reported data show that MIF is overexpressed in melanoma cells, especially in case of metastatic disease." (PMID 31013837, 2019). "Another study, aiming to understand the antagonization of the anti-melanoma immune responses by MIF, revealed that, in melanoma bearing mice, MIF derived from macrophages participates in the macrophage alternative activation." (PMID 31013837, 2019). "In agreement with previous studies, we observed that B16F10 metastatic melanoma cells express and secrete high levels of MIF in vitro, and that MIF is highly expressed in small and large lung metastatic melanoma lesions." (PMID 29875777, 2018). "The MIF inhibitor 4-iPP is so far the only immunomodulatory agent described to be effective in melanoma and has shown promising results in subcutaneous melanoma, associated with an increase in monocyte pro-inflammatory functions." (PMID 29875777, 2018). "Previous studies have shown that MIF can induce an immunosuppressive environment that supports melanoma progression." (PMID 29875777, 2018). "Upregulated MIF expression has been reported in gastric cancer, pancreatic cancer, melanoma, hepatocellular carcinoma, malignant glioma and cervical adenocarcinoma." (PMID 29707160, 2018). "In cutaneous melanoma, MIF is produced by melanoma cells to support growth and induce immunosuppression." (PMID 29875777, 2018). "Previous studies have shown that stromal and melanoma cells express high levels of MIF, supporting melanoma growth and modulating immune cells in late-stage melanoma." (PMID 29875777, 2018). "In a neuroblastoma model, MIF inhibits T cell activation in vivo, and MIF inhibition has been shown to promote conversion of melanoma patient-derived MDSCs into a more DC-like phenotype in vitro." (PMID 29864117, 2018). "Among these factors, MIF has been recently shown to have immunosuppressive activities, in many cancers, including glioblastoma, breast, pancreatic cancer, and melanoma." (PMID 29875777, 2018). "DDT shares with MIF an exacerbating role in endotoxic shock and models of melanoma, non-small cell lung carcinoma, and renal tumorigenesis, and mimics the cardioprotective effect of MIF in a mouse model of ischemia/reperfusion injury of the heart." (PMID 25888527, 2015). "Collectively these results implicate MIF in melanoma progression, but despite this evidence, little is known on the downstream signalling pathways regulated by MIF signalling, nor has this concept been evaluated in patient studies." (PMID 25168062, 2014). "The results from 5 independent experiments show that inhibition of MIF expression significantly reduces the percentage of cells in S phase compared to negative control siRNA transfection for both the MelCV and Me1007 melanoma cell lines (respectively)." (PMID 25168062, 2014).
melanoma (continued). "Having established that MIF exerts effects on the cell cycle entry and the clonogenic capacity of melanoma cells, we sought to determine which pathways are activated downstream of MIF." (PMID 25168062, 2014). "Two of the three lines most sensitive to MIF depletion are BRAF mutants (MelCV and MelRMu) indicating the effects of MIF signalling in melanoma were likely outside this pathway." (PMID 25168062, 2014). "In the current study, MIF knockdown resulted in decreased Akt phosphorylation in all melanoma cell lines tested, albeit to varying degrees." (PMID 25168062, 2014). "Collectively this suggests that activation of the Akt pathway is one of the major mechanisms whereby MIF contributes to cell cycle regulation in melanoma." (PMID 25168062, 2014). "MIF expression was depleted in human melanoma cell lines using siRNA-mediated gene knockdown and effects monitored using in vitro assays of proliferation, cell cycle, apoptosis, clonogenicity and Akt signalling." (PMID 25168062, 2014). "It is well established that MIF function is associated with two major pro-survival pathways, namely the MAPK and PI3K/Akt signalling pathways, each known to be important in melanoma." (PMID 25168062, 2014). "Collectively these findings support the notion that MIF expression is up-regulated during melanoma progression." (PMID 25168062, 2014). "All six melanoma cell lines were subjected to treatment with MIF siRNA with knockdown of MIF protein after three days of transfection confirmed relative to controls using Western blotting." (PMID 25168062, 2014). "Our in vitro analyses show that MIF functions upstream of the PI3K/Akt pathway in human melanoma cell lines." (PMID 25168062, 2014). "Inhibition of MIF expression in the G361 human melanoma cell line resulted in inhibition of proliferation, migration and tumour-induced angiogenesis." (PMID 25168062, 2014). "A combination either of B16–F10 or of shRNA targeting of MIF in the same melanoma cells with a MIF knockout (−/−) genetic background, resulted in significant reduction of tumor growth (by 47%), when compared to wild-type mice." (PMID 25050663, 2014). "Given the previous links established between MIF and Akt signalling as described in the Introduction, we focussed our efforts on investigating Akt as the likely major pathway downstream of MIF in melanoma." (PMID 25168062, 2014). "Taken together, these results provide further evidence that MIF expression regulates both cell cycle entry and the clonogeneic capacity of melanoma cells in vitro." (PMID 25168062, 2014). "In our study, of the melanoma cell lines tested for the effects of MIF inhibition, three express wildtype BRAF (Me1007, MelRM and MelFH) while the others bear the BRAF V600E mutation (MelCV, MelRMu and MM200)." (PMID 25168062, 2014). "Our data demonstrates that MIF is involved in melanoma proliferation and anchorage-independent growth, mediated through the activity of the PI3K/Akt pathway." (PMID 25168062, 2014). "MIF expression has also been shown to be of significance in a limited number of studies investigating melanoma biology." (PMID 25168062, 2014). "Our data demonstrates there was increased amount of T CD8 IL-10+ lymphocytes and IFNγ MIF when mice with melanoma were treated with BMDCs stimulated with GK-1 and loaded with MAGE-AX." (PMID 25759825, 2014). "In silico analyses of expression microarray data were used to correlate MIF expression levels in melanoma tumours with overall patient survival using a univariate Cox regression model." (PMID 25168062, 2014). "MIF depletion also significantly reduced the number of cells entering S-phase in four of six melanoma cell lines examined suggesting the proliferative capacity of the majority of melanomas have some degree of reliance on MIF expression." (PMID 25168062, 2014).